NFE2L3 (NFE2 like bZIP transcription factor 3)
Diseases named in the same sentence as NFE2L3 in open-access papers (continued):
Sharing a sentence is not in itself a finding about the gene and the disease.
cancer (continued). "The correlations between the expression of NFE2L3 and different immune signatures in TCGA pan-cancer cohort were evaluated, including immune cell infiltration, immune checkpoints, immunosuppressive cell infiltration, and immune cell markers." (PMID 35846126, 2022). "NFE2L3 plays a role in transcription of many biological processes, confers selective growth advantages to cells, and promotes cancer progression, including proliferation, invasiveness, metastasis, and angiogenesis." (PMID 35846126, 2022). "We investigated the expression, prognostic value, and relevant pathways of NFE2L3 using the datasets from public databases, including The Cancer Genome Atlas Program (TCGA), Genotype-Tissue Expression (GTEx), Cancer Cell Line Encyclopedia (CCLE), and UALCAN." (PMID 36337840, 2022). "To explore the role of NFE2L3 in RCC, we first analyzed the expression of NFE2L3 in various cancers using the datasets from TCGA database." (PMID 36337840, 2022). "Our study showed a significant positive correlation between NFE2L3 expression and most immune cell markers in TCGA pan-cancer cohort, except for UCS." (PMID 35846126, 2022). "Among the cancers analyzed, the correlations between NFE2L3 and NLRP3 are also statistically significant, among which the correlation is relatively low in LUSC (Cor = 0.158), and the correlation is highest in DLBC (Cor = 0.638)." (PMID 35664314, 2022). "The GEPIA2 database was then used to explore the top 100 genes with a similar expression pattern to NFE2L3 in the pan-cancer analysis." (PMID 35846126, 2022). "Similar to the majority of different cancer types, we demonstrated the increasing trend of NFE2L3 mRNA levels from benign to dysplastic naevi." (PMID 35378827, 2022). "Accumulation of gene mutations is one of the causes of tumorigenesis; therefore, the landscape of genetic alterations of NFE2L3 in pan-cancer were analyzed." (PMID 35846126, 2022). "To investigate the molecular function of NFE2L3 in pan-cancer, we performed a comprehensive and integrated analysis of NFE2L3 by combining multiple bioinformatic approaches." (PMID 35846126, 2022). "NFE2L3 expression is closely related to DNA methylation, genetic alteration, immune signature, and tumor cell functional status in pan-cancers." (PMID 35846126, 2022). "The correlations between NFE2L3 expression and DNA methylation, genetic alterations, immune features, and tumor cell functional status in pan-cancers was also investigated." (PMID 35846126, 2022). "As a homolog of NFE2L2, NFE2L3 has been proven to be related to multiple phenotypes of malignant tumors as well, including proliferation and epithelial-mesenchymal transition (EMT)." (PMID 35664314, 2022). "The correlation between NFE2L3 expression and clinicopathological stage in pan-cancer was also investigated." (PMID 35846126, 2022). "A significant positive correlation between the expression of NFE2L3 and the level of immune cell infiltration in TCGA pan-cancer cohort was demonstrated, except for COAD, OV, UCEC, and UCS." (PMID 35846126, 2022). "It was also found that the β-catenin/TCF4 complex of the Wnt signaling pathway activates the expression of NFE2L3 transcripts in colon as well as other cancer cells." (PMID 35091681, 2022). "The correlations between NFE2L3 expression and immune or molecular subtypes in TCGA pan-cancer cohort from the TISIDB database were investigated." (PMID 35846126, 2022). "In conclusion, the study revealed the essential biological function of NFE2L3 in pan-cancers and showed that NFE2L3 has the potential to be used as an effective therapeutic target and tumor diagnostic marker." (PMID 35846126, 2022). "The total genetic alteration frequency of NFE2L3 was 2.2% (244/10,950) in TCGA pan-cancer cohort, and the highest alteration frequency of NFE2L3 was approximately 6.4% in patients with UCEC." (PMID 35846126, 2022).
cancer (continued). "Nfe2l3 transcripts are elevated in the colonic mucosa in an inflammation-induced cancer model in mice following treatment with AOM/DSS." (PMID 35091681, 2022). "Through pan-cancer analysis of samples in TCGA, it can be seen that compared with normal tissues, NFE2L3 is highly expressed in almost all kinds of tumor tissues." (PMID 35664314, 2022). "Remarkable upregulation of the NRF2 (NFE2L2)-related transcription factor NRF3 (NFE2L3) in several cancer tissues and its correlation with poor prognosis strongly suggest the physiological function of NRF3 in tumors." (PMID 31288376, 2019). "The acRIP-seq results showed that the abundance of ac4C in NFE2L3 was significantly upregulated in cancer tissues, that ac4C modification mainly occurred in the common sequences of CCHCCRCC (H = G or A, R = G or A or U), and that the ac4C modification sites all existed in the CDS region of NFE2L3." (PMID 40169553, 2025). "Accumulating evidence suggests that NFE2L3 is crucial for the development of cancer." (PMID 38514488, 2024). "The research revealing the correlation of immune cell infiltration with NFE2L3 may open unique avenues for precise cancer therapeutics against cancers." (PMID 38514488, 2024). "However, no studies to our knowledge have evaluated the significance of NFE2L3 expression in pan-cancer analyses." (PMID 35846126, 2022). "However, there are limited studies on NFE2L3 in different cancer types, thus it is necessary to comprehensively analyze NFE2L3 expression in pan-cancers." (PMID 35846126, 2022). "Furthermore, the expression of NFE2L3 was shown to be significantly correlated with the expression of six genes at the intersection in TCGA pan-cancer cohort by the GEPIA2 database." (PMID 35846126, 2022). "However, a significant positive correlation between NFE2L3 expression and immune checkpoint expression in TCGA pan-cancer cohort was demonstrated except for READ, UCEC, and UCS." (PMID 35846126, 2022). "This study showed that NFE2L3 expression was significantly correlated with various immune characteristics in TCGA pan-cancer, including immune cell infiltration, immune checkpoints, immunosuppressive cell infiltration, immune cell markers, immunomodulators, immune subtypes, and molecular subtypes." (PMID 35846126, 2022). "Our study showed that NFE2L3 expression was upregulated in most cancers, suggesting that NFE2L3 may play an important role in promoting cancer progression." (PMID 35846126, 2022). "The overall alteration frequency of NFE2L3 was 2.2% (244/10,950) in TCGA pan-cancer cohort." (PMID 35846126, 2022). "In summary, our study indicated that NFE2L3 may be an important molecular biomarker for the diagnosis and prognosis of pan-cancer." (PMID 35846126, 2022). "Our study comprehensively analyzed NFE2L3 expression in pan-cancers using different databases." (PMID 35846126, 2022). "Thus, DNA methylation levels of NFE2L3 in normal and primary tumor tissues in pan-cancer were assessed." (PMID 35846126, 2022). "We also analyzed genomic alterations of NFE2L3 in pan-cancer cells." (PMID 35846126, 2022). "However, the potential roles of NFE2L3 in tumorigenesis and cancer progression remain to be further elucidated." (PMID 34926237, 2021). "Intriguingly, the effects of NFE2L3 on various cancers are very different." (PMID 33173129, 2020). "NFE2L3 is located in the cytoplasm under physiological conditions, and during the occurrence of malignant tumors, it translocates into the nucleus with the help of the aspartic protease DDI2 as a transcription factor to regulate the expression of downstream genes." (PMID 33123284, 2020). "Furthermore, knockdown of NFE2L3 significantly impairs both migration ability in HepG2 cells, which was consistent with the data that NFE2L3 is positive correlation with malignant metastasis status of cancer." (PMID 33123284, 2020).
cancer (continued). "Knockdown NFE2L3 or LASP1 restored the changes in cell proliferation and migration caused by overexpression of NAT10, indicating that NAT10 might perform similar functions through NFE2L3/LASP1 signalling in other cancers." (PMID 40169553, 2025). "Therefore, to gain a better understanding of the role of NFE2L3, this review offers insights into the discovery, structure, function, and recent advancements in the study of NFE2L3 to lay the groundwork for the development of NFE2L3-targeted therapies for cancer." (PMID 39149514, 2024). "In summary, our study demonstrated the importance of NFE2L3 in the diagnosis and prognosis of pan-cancer, which could be conducive to further exploring its mechanism in tumorigenesis and development and provide a comprehensive analysis basis for cancer treatment in the future." (PMID 35846126, 2022). "In addition, silencing NFE2L3 inhibited the cell cycle, increased the proportion of apoptotic cells, and may play a role in promoting cancer through the EMT signaling pathway." (PMID 34783304, 2021). "Moreover, the NFE2L3 gene has been shown to promote cancer in additional studies." (PMID 34783304, 2021). "The mechanism of NFE2L3 in cancers is entirely different from NRF2, but limited research has evaluated the significance of NFE2L3 as an innovative indicator in malignancies." (PMID 38514488, 2024). "Therefore, to gain a better understanding of the role of NFE2L3 in disease, this review offers insights into the discovery, structure, function, and recent advancements in the study of NFE2L3 to lay the groundwork for the development of NFE2L3-targeted cancer therapies." (PMID 39149514, 2024). "In contrast to the well‐characterized NRF2, little is known about the target genes, mechanisms of action, and roles in cancer development and progression of the related NRF3 (NFE2L3) protein." (PMID 37807968, 2023). "A significant positive correlation was also shown between NFE2L3 expression and the levels of Tregs, MDSC, and CAF in TCGA pan-cancer cohort, except for ACC, CESC, and UCS." (PMID 35846126, 2022). "These genes are PLAUR, UCN, PABPC1L, SLC16A12, NFE2L3, and KCNAB1, and some of them have been previously reported in multiple types of cancer." (PMID 35211477, 2021). "Three genes (NFE2L3, GTF2IRD1, and PPM1H) were significantly differentially expressed between cancer and normal cells or between cancer and IBDs with greater than 2-fold changes (all P < 0.001)." (PMID 30988394, 2019). "Accumulated evidence suggests a physiological relationship between the transcription factor NRF3 (NFE2L3) and cancers." (PMID 28970512, 2017). "The first were tightly regulated, through MELK, BRCA2, KIF14, BUB1, and TOP2A, by five TFs (NFE2L3, RUNX1, RUNX2, BHLHE40, and the aging cancer-specific SOX11), two LncRNAs (ST7OT1 and CDKN2BAS), and four miRNAs (miR-21-5p, miR-363-3p, miR-873-5p, and miR-138-1-3p)." (PMID 37191407, 2023). "This study showed that NFE2L3 expression was also significantly positively correlated with three immunomodulators, including immunoinhibitory, immunostimulatory, and MHC molecules in TCGA pan-cancer cohort." (PMID 35846126, 2022). "In addition, the correlation between NFE2L3 methylation levels and NE2L3 mRNA expression levels, tumor stemness, immune subtypes, and pan-cancer prognosis was evaluated." (PMID 35846126, 2022). "Pan-caner analysis indicated that NFE2L3 might promote the differentiation of Th2 cells through the IL-2/STAT5/NLRP3 signaling pathway in MPM and many other cancers." (PMID 35664314, 2022). "The PAb anti NFE2L3 recognized the recombinant protein and several bands which had the molecular weight of 77-, 65-, 30- and 28 kDa only in leukocytes but not the cancer cell lines HT29 and SW620." (PMID 22321245, 2012).
tumor (36 papers, 2012 to 2026). "NFE2L3 was expressed at high levels in most tumor cells according to the CancerSEA analysis and was closely associated with various tumor cell functional states, such as apoptosis, differentiation, inflammation, and stemness." (PMID 35846126, 2022). "In our study, NFE2L3 was detected to be highly expressed in MPM tumor tissues, and the higher expression level is associated with poor prognosis." (PMID 35664314, 2022). "Distally, deficiency of NFE2L3 coincides with a loss of mast cells and a decrease in tumor burden, whereas proximally it promotes Treg infiltration and subsequent reduction of inflammation." (PMID 35091681, 2022). "We showed that loss of NFE2L3 leads to less inflammation and a change in the tumor microenvironment, with a reduced number of mast cells and an increase in regulatory T cells, mediated through signaling via the IL33 and RAB pathways." (PMID 35091681, 2022). "In our studies, while loss of NFE2L3 decreased the overall tumor burden, it preferentially did so in the distal section of the colon." (PMID 35091681, 2022). "NFE2L3 mutations occurred in most tumor types, with the top three tumors, UCEC, BLCA, and ESCA, having high NFE2L3 mutations (>6%)." (PMID 35846126, 2022). "Since anchorage-independent growth is a hallmark of tumorigenesis 19, an animal xenograft model was next used to test the effect of NFE2L3 deficiency elicits on the carcinogenesis of tumor cells." (PMID 33123284, 2020). "Recent studies showed the first in vivo function of NFE2L3 and its link to tumour development using a NFE2L3 - deficient mice." (PMID 22321245, 2012). "NFE2L3 is not only involved in cell cycle regulation but also associated with the apoptosis, proliferation and inflammation of tumor cells, suggesting that it may be involved in disulfidptosis-related processes." (PMID 40295497, 2025). "Furthermore, for DSS, the higher expression of NFE2L3 was associated with a worse prognosis in five tumor types, including KIRC, LGG, LIHC, MESO, and PAAD." (PMID 35846126, 2022). "Hypo-high expression of NFE2L3 may cause the tumor cells escaping from the detection of the immune system by inhibiting the anti-tumor immune effect, and consequently lead to proliferation and metastasis of ccRCC." (PMID 31777602, 2019). "In vitro and in vivo experiments support NFE2L3 as an oncogene involved in the process of tumor formation." (PMID 38514488, 2024). "It is worth mentioning that the inflammatory factor TNF-α can promote RELA to bind to the first intron of NFE2L3 to activate its transcription, thereby affecting tumor progression." (PMID 39149514, 2024). "James Saliba demonstrated that the deletion of NFE2L3 results in decreased inflammation and a shift in the tumor microenvironment via the IL33 and RAB pathways." (PMID 38514488, 2024). "Recent research, particularly in the past 5 years, has shed light on NFE2L3’s participation in diverse biological processes, including cell differentiation, inflammatory responses, lipid homeostasis, immune responses, and tumor growth." (PMID 39149514, 2024). "NFE2L3 enhances tumor cell migration ability by affecting the EMT through Wnt/β-catenin signaling pathway." (PMID 38514488, 2024). "Taken together, these results strongly imply that NFE2L3 plays a protective role against skin cells, especially during tumor growth." (PMID 39149514, 2024). "Through further screening, we found that NFE2L3 was highly expressed in tumor tissues of patients with MPM and both its mRNA expression level and DNA methylation level was highly correlated with the infiltration level of Th2 cells." (PMID 35664314, 2022). "The expression level and functional status of NFE2L3 in single tumor cells using the CancerSEA database was determined." (PMID 35846126, 2022). "Our study demonstrated that the DNA methylation levels of NFE2L3 were downregulated in most tumors and negatively correlated with the expression levels of NFE2L3 mRNA and the tumor cell stemness score." (PMID 35846126, 2022).
tumor (continued). "We further found that tumor samples from Nfe2l3 knockout animals displayed significantly reduced IL33 expression when compared to wild type." (PMID 35091681, 2022). "The immune response of tumors is an important process in tumor development, thus the role of NFE2L3 in tumor immune regulation was investigated by analyzing the immune features and immunotherapeutic responses." (PMID 35846126, 2022). "For PFS, higher expression of NFE2L3 had a poor prognosis in seven tumor types, including GBM, KIRC, LGG, LIHC, MESO, PAAD, and THYM." (PMID 35846126, 2022). "NFE2L3 was expressed at high levels in a variety of tumor cell lines, according to the CCLE database analysis." (PMID 35846126, 2022). "Together, these data strongly suggest a location- and genotype-dependent role of NFE2L3 in the modulation of inflammation and tumor development in our CRC model." (PMID 35091681, 2022). "Our studies revealed that Nfe2l3−/− mice exhibit significantly less inflammation in the colon, reduced tumor size and numbers, and skewed localization of tumors with a more pronounced decrease of tumors in the distal colon." (PMID 35091681, 2022). "The potential of NFE2L3 in tumor immunotherapy was explored further by conducting a correlation analysis between the expression of NFE2L3 and immune characteristics." (PMID 35846126, 2022). "In tumor samples, Nfe2l3 knockout mice displayed significantly more resting mast cells in comparison to wild type animals that in turn exhibited significantly more activated mast cells." (PMID 35091681, 2022). "Using digital spatial profiling, we found that Nfe2l3-/- mice presented elevated Treg counts and immune checkpoint signatures in the tumour microenvironment." (PMID 36289474, 2022). "NFE2L3 also had promising efficacy in tumor diagnosis, especially in the diagnosis of CHOL, COAD, KICH, READ, and STAD." (PMID 35846126, 2022). "Herein, these results manifested a potential relevance between NFE2L3 expression and tumor progression." (PMID 36337840, 2022). "Our studies revealed that Nfe2l3 knockout mice display a significant reduction in both tumour size and numbers compared to wild type animals, with Nfe2l3+/- mice exhibiting an intermediate phenotype." (PMID 36289474, 2022). "In most tumor cells, NFE2L3 expression was positively correlated with differentiation, angiogenesis, apoptosis, inflammation, and tumor cell stemness however, NFE2L3 expression negatively correlated with DNA damage, DNA repair, and invasion." (PMID 35846126, 2022). "We found that NFE2L3 plays a role in promoting tumor metastasis, which led us to study the mechanism by which NFE2L3 promotes metastasis." (PMID 34783304, 2021). "After tumor purity correction, we found that NFE2L3 expression levels were negatively correlated with the infiltration level of CD4 T cells and significantly positively correlated with the infiltration level of CD8 T cells." (PMID 34783304, 2021). "Meanwhile, silencing of NFE2L3 also shows an inhibitory effect on tumor growth in HepG2 cell xenografts in vivo." (PMID 33123284, 2020). "Subcutaneous tumorigenesis experiments and immunohistochemical also support NFE2L3 as an oncogene whose high expression is involved in tumor cell malignant proliferation." (PMID 33123284, 2020). "Real-time polymerase chain reaction (PCR) results showed that higher NFE2L3 expression levels were identified in paired tumor samples than in paratumor samples (48 paired samples)." (PMID 31191746, 2019). "RCAN1.4 knockdown promotes tumor growths, which is mediated by nuclear factor erythroid 2-like 3 (NFE2L3)." (PMID 29416595, 2018). "Furthermore, interferon‐associated basal‐like tumor cells secrete BMP2, which induces the expression and activity of NFE2L3, a transcription factor specific to MMP11+ mCAFs, promoting WNT5A expression." (PMID 40552583, 2025). "We observed both tumor immune and molecular subtypes of NFE2L3 in DSC." (PMID 38514488, 2024).